BRAF (B-Raf proto-oncogene, serine/threonine kinase)
Diseases named in the same sentence as BRAF in open-access papers (continued):
Sharing a sentence is not in itself a finding about the gene and the disease.
lung adenocarcinoma (continued). "BRAF V600E mutation, a missense mutation in exon 15 resulting in valine substitution for glutamate at position 600 within the kinase domain of BRAF oncogene, is found in a subset of lung adenocarcinoma (ADC)." (PMID 31234388, 2019). "Corresponding with reported activity of NF1 as a tumor suppressor and negative regulator of RAS in lung adenocarcinomas, truncating mutations in NF1 tend to be mutual exclusive with activating mutations in RAS and BRAF (TCGA) in these tumors." (PMID 30858928, 2019). "The BRAF inhibitor dabrafenib and the MEK (methyl ethyl keytone) inhibitor trametinib have been used clinically to treat BRAF-positive lung adenocarcinoma patients." (PMID 29435193, 2018). "This review presents the current knowledge of the processes of tumorigenesis and progression in early lung adenocarcinoma, with a focus on its clinicopathological characteristics and their associations with driver mutations (EGFR, KRAS, and BRAF)." (PMID 29690599, 2018). "The lung adenocarcinoma dataset SRA ERP001058 contains 41 tumors with known targetable or oncogenic mutations in 6 genes: EGFR, KRAS, NRAS, MET, BRAF and CTNNB1." (PMID 30255803, 2018). "EGFR, KRAS, HER2, BRAF, and PIK3CA mutations are these important genetic alterations in the targeted therapies of lung adenocarcinoma." (PMID 29518290, 2018). "This review summarizes the state of knowledge of tumorigenesis and progression of early lung adenocarcinoma, with a special focus on its clinicopathological characteristics and their associations with driver mutations (EGFR, KRAS, and BRAF)." (PMID 29690599, 2018). "Similar findings were observed in EGFR mutant lung adenocarcinoma preclinical models and individuals with BRAF V600E lung adenocarcinoma." (PMID 29152593, 2017). "Briefly, among newly detected mutations in lung adenocarcinoma, AKT, BRAF, FGFR2, HRAS, and KIT mutations were detected in one sample (1.3%), MAP2K in two samples (2.6%), MET in 4 samples (5.9%), and FGFR3 in 5 samples (7.4%)." (PMID 28404952, 2017). "Five common oncogenes, Kras, EGFR, ALK, ERBB2, and BRAF are represented in more than 50 % of lung adenocarcinomas." (PMID 26884725, 2016). "The driver genes involved in lung adenocarcinoma include KRAS, EGFR, ALK, and BRAF, and those implicated in lung squamous cell carcinoma (LSCC) include PIK3CA, FGFR1, EGFR, PDGFRA, and DDR2." (PMID 26373952, 2015). "BRAF copy number gain is rare in lung adenocarcinomas, however, it does occur in the aggressive V600E subtype." (PMID 25621040, 2015). "Recent genomic studies in lung adenocarcinoma have identified other potential therapeutic targets, such as mutations in KRAS, HER2 and BRAF, ROS1 rearrangements, RET fusions and MET amplification." (PMID 25789627, 2015). "Typically, increases in BRAF copy number are moderate; however, in V600E lung adenocarcinomas, BRAF copy number increases occur with significant prevalence." (PMID 25621040, 2015). "‘Exclusivity plots’ for COAD revealed mutations in BRAF to be negatively associated with mutations in KRAS, to a degree similar to that we observed for co-existing mutations of EGFR and KRAS in lung adenocarcinoma." (PMID 26047463, 2015). "Concomitant BRAF and AKT mutations were observed in 2 lung adenocarcinomas, both of which had a BRAF p.V600E (c.1799 T > A) mutation." (PMID 26498038, 2015). "EGFR, KRAS, HER2, BRAF mutation and ALK fusion were mutated in 25.2%, 6.5%, 1.9%, 0.9% and 3.7% of lung adenocarcinomas." (PMID 25198510, 2014). "According to specific oncogenic driver mutations, lung adenocarcinoma is divided to molecular subtypes such as EGFR, KRAS, ALK, HER2, BRAF and so on." (PMID 25198510, 2014).
lung adenocarcinoma (continued). "In conclusion, our work illustrated the mutation spectrum of EGFR, KRAS, HER2, BRAF and ALK in lung adenocarcinoma, as well as confirmed that hTERT 5′ promoter region mutation rarely occurred in NSCLC samples." (PMID 25198510, 2014). "We have screened the prevalence of known driver mutations of EGFR, KRAS, HER2, BRAF and ALK in a cohort of 107 lung adenocarcinoma sample with complete prognostic information." (PMID 25198510, 2014). "Because mutations of EGFR, KRAS, HER2, BRAF, as well as ALK fusions have been well established to be existed in lung adenocarcinoma, these mutation and fusion genes that ‘drives’ lung adenocarcinoma were not screened in lung squamous cell carcinoma." (PMID 25198510, 2014). "Several other driver molecular alterations have been identified in lung adenocarcinoma, including somatic mutations of KRAS, BRAF, STK11, DDR2 and members of the FGFR family, as well as ALK rearrangements." (PMID 24236184, 2013). "This was clearly the case in a few of our specimens, including both colorectal and lung adenocarcinomas, where quantitative ASLNAqPCR results of KRAS and BRAF analysis showed that mutations were present in a minority of the tumor cells." (PMID 22558339, 2012). "Major recurrent mutations in lung adenocarcinoma have been found to occur in EGFR, KRAS, HER2, BRAF, ALK and ROS1." (PMID 22140546, 2011). "The prevalence of EGFR, BRAF, and PIK3CA mutations in lung adenocarcinomas was 6 (13/234), <1 (1/156), and 2% (2/132), respectively." (PMID 17487277, 2007). "Other alterations, such as ALK rearrangements and BRAF mutations, also appear more frequently in radon-exposed populations and are frequently observed in non-smoking lung adenocarcinomas." (PMID 40823246, 2025). "BRAF mutations are relatively rare in NSCLC (2.3 % of lung adenocarcinoma) and often appear in never-smokers." (PMID 40502411, 2025). "In this study, we selected a panel of lung adenocarcinoma cell lines harboring major mutations commonly found in LUAD tumors, more specifically mutations of EGFR (H1975), KRAS (PF139) and BRAF (PF901) oncoproteins, furthermore, we also included one cell line with no known driver mutations (H838)." (PMID 39227650, 2024). "Two patients with stage IV lung adenocarcinoma harboring a BRAF class 3 mutation without other concurrent genomic driver alterations were treated with erlotinib after standard treatments." (PMID 39637338, 2024). "Accordingly, we addressed tumor heterogeneity by investigating cells harboring major mutations that are commonly found in lung adenocarcinoma, utilizing H1975 (EGFR L858R and T790M), PF901 (BRAF V600E), PF139 (KRAS G12C), and H838 (triple wild type with no known driver mutation) cell lines." (PMID 39227650, 2024). "For example, the inhibition of mutant-EGFR in lung adenocarcinoma cells or mutant-BRAF in thyroid cancer cells was shown to induce the secretion of IL6 and the subsequent activation of STAT3, and in both cases, blocking the STAT3 function largely prevented the emergence of drug-tolerant cells." (PMID 38473364, 2024). "Lung adenocarcinoma may harbor both activating and resistance mutations of the EGFR gene, and further, mutations of KRAS and BRAF oncogenes." (PMID 38953007, 2024). "According to one Korean dataset, there were four patients (1.8%) with a BRAF mutation among 222 Stage III/IV lung adenocarcinoma patients without EGFR/ALK aberrations." (PMID 37374289, 2023). "Therefore, the MASE‐CE assay for detecting KRAS, NRAS, BRAF mutations and MSI status can also be applied to patients with other cancers, including pancreatic and lung adenocarcinomas." (PMID 36583506, 2023).
lung adenocarcinoma (continued). "Several previous studies have investigated the incidence, distribution, and prognosis of BRAF mutant lung adenocarcinoma, but, partly due to relatively small sample size and the retrospective nature, the results have been demonstrated as inconclusive and/or contradictory." (PMID 35454926, 2022). "Here, we report the first case of a successful neoadjuvant-targeted therapy with BRAF and MEK inhibitors followed by radical surgical excision with major pathologic response (MPR) in a patient with stage IIIA lung adenocarcinoma (LUAD) harboring BRAF V600E mutation." (PMID 36003777, 2022). "BRAF is a serine/threonine kinase, which is mediated by the RAS‐RAF‐MEK‐ERK signaling pathway, and BRAF mutations have been previously observed in about 1%–5% of lung adenocarcinomas." (PMID 33215864, 2021). "Here, we describe the case of a 77-year-old male with a history of BRAF-positive lung adenocarcinoma with metastasis to the brain, adrenals, and small bowel (jejunum), currently on dual therapy with dabrafenib and trametinib, who presented with refractory epistaxis." (PMID 34466299, 2021). "We report a case of impressive radiological and ctDNA response under dabrafenib, trametinib, and osimertinib in an advanced EGFR-mutant lung adenocarcinoma patient who developed BRAF V600E as one of the acquired resistance mechanisms to second-line osimertinib." (PMID 33580193, 2021). "Nevertheless, our in vitro and in vivo findings fully support the notion that EGFR/MEK combination might be a viable option to overcome BRAF-driven resistance in patients with EGFR-mutant lung adenocarcinoma." (PMID 34921211, 2021). "Lower than expected variant allele frequency of IDH1/2 mutants and coexistence of IDH1/2 mutations with known trunk drivers in the BRAF, EGFR, and KRAS genes suggest they could be branching drivers leading to subclonal evolution in lung adenocarcinomas." (PMID 32333643, 2020). "We estimated the clonality of BRAF variants in 22 (3 V600, 19 non-V600), 44 (33 V600; 11 non-V600), and 187 (156 V600, 21 non-V600) lung adenocarcinoma (LUAD), colorectal adenocarcinoma (COAD), and melanoma skin cancer (SKCM) tumors, respectively." (PMID 31723142, 2019). "Type I and II LCNECs harbor key genomic alterations and oncogenic mutations, which are commonly found in SCLC, lung adenocarcinoma or squamous cell carcinoma (e.g., in RAS genes, BRAF, NFE2L2, as well as in STK11 and KEAP1 in the case of type I LCNECS, and RB1 losses in the case of type II LCNECs)." (PMID 29535388, 2018). "Of interest, no BRAF mutations were found in lung adenocarcinomas that coexisted with BRAF-mutated AAH lesions, whereas four of five cases of BRAF-mutated AAH tumors coexisted with EGFR-mutated adenocarcinomas." (PMID 29690599, 2018). "The mutual exclusivity of BRAF and KRAS mutations in AAHs and the disparate pattern of mutations in the paired lung adenocarcinomas suggest divergent pathways in the pathogenesis of preneoplastic lesions of lung adenocarcinomas." (PMID 30060526, 2018). "Other mutually exclusive genetic alterations, which have been reported to work as driver mutations in lung adenocarcinoma, include translocations of ALK, ROS1, RET, NTKR1, NRG2, ERBB4, and BRAF, and mutations of KRAS, BRAF, ERBB2, NRAS, HRAS, MAP2K1, NF1, and RIT1." (PMID 27005669, 2016). "The present study hypothesized that an increase in BRAF copy number may be correlated with certain clinicopathological features of lung adenocarcinoma in Japanese patients." (PMID 25621040, 2015). "A total of 1356 lung adenocarcinoma cases from April 2007 to May 2013 were sequenced for EGFR kinase domain mutations, KRAS mutations, HER2 kinase domain mutations, BRAF mutations, ALK fusions, ROS1 fusions, RET fusions and AKT1 mutations." (PMID 26486077, 2015).
lung adenocarcinoma (continued). "The BRAF gene copy number was analyzed using quantitative polymerase chain reaction amplifications in 29 surgically treated lung adenocarcinoma cases without EGFR or Kras mutations from Nagoya City University Hospital (Nagoya, Japan)." (PMID 25621040, 2015). "In the present study, increased BRAF gene copy number was identified in 10.3% of Japanese lung adenocarcinoma patients without EGFR or Kras mutations." (PMID 25621040, 2015). "Clinicopathologic comparisons between HER2 and BRAF mutation positive and negative Lung adenocarcinomas." (PMID 26102513, 2015). "This contrasts with findings in BRAF*-driven lung adenocarcinoma model where BRAF* acts not only as an initiating oncogene but shown to be required for maintenance, highlighting the context/lineage specific role(s) of an oncogenic event in genesis, progression and maintenance." (PMID 19079609, 2008). "Mutations observed in EGFR, KRAS, BRAF, and FGFR4 in lung adenocarcinomas." (PMID 17487277, 2007). "Moreover, in lung adenocarcinoma (LUAD) driven by B-Raf proto-oncogene (BRAF), reducing Cu levels inhibited the initiation of ULK-dependent autophagy, thereby bolstering the antitumor efficacy of traditional MAPK pathway inhibitors that induced the upregulation of protective autophagy." (PMID 38918694, 2024). "In addition, mutations in other genes like KRAS, BRAF or HER2 have been reported to be negative prognostic biomarkers in patients with lung adenocarcinoma, making the prognostic landscape more complex." (PMID 35012520, 2022). "The oncogenic mechanism of activating BRAF mutations, such as BRAFV600E, is known to promote MEK-ERK activation; however, the biological role of kinase-inactive BRAF mutations, which are more common in lung adenocarcinoma than the activating BRAFV600E mutation, is not known." (PMID 29690599, 2018). "The aim of our study was to analyze the mutational rate of EGFR, KRAS, BRAF, ERBB2 and PI3KCA in a large cohort of 2,219 unselected French patients presenting in routine clinical practice for first line treatment decision of metastatic or recurrent lung adenocarcinoma." (PMID 28881604, 2017). "Although BRAF copy number gain has been investigated in thyroid tumors, to the best of our knowledge, the association between BRAF gene mutation and copy number gain in Japanese lung adenocarcinoma patients has not previously been reported." (PMID 25621040, 2015). "Thus, BRAF copy number gain may serve as a marker of the more aggressive behavior of V600E lung adenocarcinoma." (PMID 25621040, 2015). "We selected formalin-fixed paraffin embedded lung adenocarcinoma specimens that showed discrete areas of different subtypes, extracted subtype DNA samples from those areas and screened for mutations in hotspot regions of the EGFR, KRAS and BRAF genes using high resolution melting." (PMID 24742923, 2014). "In addition to EGFR mutations and ALK rearrangements, genomic studies have also identified frequent copy number changes and somatic mutations affecting components of key signaling pathways in adenocarcinoma of the lung including KRAS, Her2, BRAF, C-MET, MEK1 and PIK3CA." (PMID 25562798, 2012). "The top five actionable alterations in lung adenocarcinomas were reported in EGFR (43 %), ALK (5 %), BRAF (5 %), KRAS (5 %), and ROS1 (2 %) genes." (PMID 40821453, 2025).
lung adenocarcinoma (continued). "We reported an elderly, non-smoking woman with unknown primary lung adenocarcinoma harboring a BRAF V600E mutation and high PD-L1 expression, who presented with high tumor burden including multistation mediastinal lymph-node metastases and massive pleural and pericardial effusions." (PMID 41333480, 2025). "Recent Asian expert consensus has reported that the percentage of EGFR alterations in lung adenocarcinoma is higher among East Asian compared to Western population (40–55% vs. 12–25%), while KRAS, BRAF, and ROS1 are lower, with HER2 and MET are nearly similar." (PMID 38245692, 2024). "A 70‐year‐old woman with stage IVA lung adenocarcinoma underwent comprehensive genomic profiling (CGP) after failure of second‐line therapy, which revealed BRAF V600_W604 deletion–insertion." (PMID 38766698, 2024). "In lung squamous cell carcinoma and lung adenocarcinoma, EZH2 expression is positively correlated with BRAF (r = 0.2397, p < 0.0001) and KRAS (r = 0.3167, p < 0.001) gene expression." (PMID 37069494, 2023). "Likewise, the absence of BRAF V600E mutation could not definitively preclude an MLH1 methylation in this lung adenocarcinoma." (PMID 33608032, 2021). "In the present study, we describe the molecular epidemiology of EGFR, KRAS, BRAF, ALK and MET genetic alterations and their correlations with the demographic and clinical characteristics of 1440 Sardinian patients with lung adenocarcinoma." (PMID 31711449, 2019). "Furthermore, the coexpression of activating KRAS mutations and inactivating BRAF mutations in mouse lung cells markedly enhanced tumor initiation, a phenomenon mediated by CRAF kinase activity, and effectively accelerated tumor progression to advanced lung adenocarcinomas." (PMID 29690599, 2018). "In cohort 1, the HS values of EGFR, KRAS, HER2, BRAF, and PIK3CA were calculated to estimate intratumor genetic heterogeneity in lung adenocarcinoma." (PMID 29518290, 2018). "Analyses of five driver genes, including EGFR, KRAS, BRAF, HER2 and EML4-ALK, were performed in patients with treatment naïve lung adenocarcinoma." (PMID 25789627, 2015). "From August 2011 to November 2013, a total of 1772 patients with treatment-naïve lung adenocarcinoma were enrolled as Cohort 1 for EGFR, KRAS, BRAF and HER2 genetic analyses." (PMID 25789627, 2015). "Current international guidelines recommend analysis of the following seven genes before starting palliative intent therapy for lung adenocarcinoma: KRAS, EGFR, ALK, ROS1, HER2, BRAF, RET." (PMID 26018876, 2015). "Patient#A was a 69-year-old male, former smoker, treated for a lung adenocarcinoma TTF1+ without EGFR, KRAS, or BRAF mutation or ALK or ROS1 translocation but an expression of 100% of PDL1 on the tumor cell." (PMID 37370798, 2023). "Patient#B was a 53-year-old male, current smoker, with a lung adenocarcinoma TTF1+ PDL1 0% without EGFR, KRAS, or BRAF mutation or ALK and ROS1 translocation but STK11 mutation." (PMID 37370798, 2023). "Now, we are screening some lung adenocarcinoma cell lines harboring gene mutations, such as EGFR mutations, ALK rearrangement, KRAS mutations, and BRAF mutation, and other cell lines without gene mutations to detect MTAP gene and protein expression." (PMID 31965001, 2020). "Intriguingly and interestingly, no BRAF mutants were observed among the paired lung adenocarcinomas of BRAF-mutant AAHs; however, in four of the five BRAF-mutant AAHs, the paired lung adenocarcinomas exhibited driver EGFR mutations." (PMID 30060526, 2018). "BRAF was the most mutated gene in AAH lesions, but three of the four patients with mutated BRAF in AAHs had not mutated BRAF in the matched lung adenocarcinoma." (PMID 30060526, 2018).